MMP2 (matrix metallopeptidase 2)
Diseases named in the same sentence as MMP2 in open-access papers (continued):
Sharing a sentence is not in itself a finding about the gene and the disease.
cancer (continued). "The involved proteases in migration and invasion, in particular, MMP-2 and MMP-9 were reported to play an important role in cancer invasion and metastasis." (PMID 23431332, 2013). "The expression and activation of extracellular proteases such as MMP-2 and MMP-9 allow cancer cells to degrade extracellular matrix proteins, thus rendering the migration invasive." (PMID 24023938, 2013). "The overexpression of MMP-2 and MMP-9 in malignant tumors has been demonstrated to develop a vasculature by angiogenesis." (PMID 24137381, 2013). "This requirement is supported by the demonstration that MT1-MMP is capable of cleaving MMP-2 to form a pro-MMP-2/MT1-MMP/TIMP-2 complex, which enhances the concentration of active MMP-2 at the leading edge of invading cancer cells." (PMID 23967226, 2013). "Here we found the protein activity of MMP-2 and MMP-9, which are involved in degradation of extracellular matrix and play vital roles in cancer cell migration and invasion." (PMID 23764122, 2013). "Of these proteases, MMPs such as MMP-2, MMP-9 and the uPA are thought to play a key role in cancer cell invasion and metastasis." (PMID 23874773, 2013). "MMP-2, MMP-9 and u-PA play important roles in degrading basement membranes and are intricately involved in cancer invasion and metastasis." (PMID 24039823, 2013). "Some authors reported that the matrix-degrading activity of MMP-9 is nearly 25 times that of MMP-2, and that MMP-9 is more important for the metastatic potential of carcinoma than MMP-2." (PMID 23281640, 2013). "Several recent studies demonstrated that high preoperative serum or plasma MMP-2, MMP-9 and TIMP-1 antigen levels are strong predictive factors for poor prognosis in patients with CRC and their determination might be useful for identification of patients with higher risk for cancer recurrence." (PMID 23202950, 2012). "MMP-2 and MMP-9 degrade type IV collagen, and have important roles in the vascular invasion of cancer cells." (PMID 22159401, 2012). "In this study, it was found that luteolin supressed the activation of AKT, ERK, mTOR, P70S6K, MMP-2, and MMP-9 in a concentration-dependent manner in PC-3 cancer cells." (PMID 23300633, 2012). "Therefore, MMP-2 may play a more important role in the cancer cells migration and invasion." (PMID 23226337, 2012). "Furthermore, an increase in serum adiponectin might reflect favourable effects of radioiodine administration on cardiovascular and cancer risk factors, while an increase in TIMP-2 (principal MMP-2 inhibitor) might lead to a decrease in free MMP-2 concentrations." (PMID 23107223, 2012). "Among the involved proteases, MMP-2, MMP-9, and u-PA are most vital for the degradation of base membranes, and are therefore deeply involved in cancer invasion and metastasis." (PMID 22363545, 2012). "In this study, we focused on the modulating effect of NM on the activities of MMP-2 and -9, TIMPs and u-PA in human breast (MBA-MD-231, MCF-7), cervical (HeLa), uterine (SK-UT-1) and ovarian (SK-OV-3) cancer cell lines." (PMID 22736175, 2012). "The importance of basement membrane remodeling and the role of MMP-2 and activating enzymes, like MT1-MMP, in this process has been shown in various developmental and cancer studies." (PMID 23091646, 2012). "MMP-2 and MMP-9 are proteolytic enzymes that digest the components of the basement membrane facilitating metastasis of malignant tumors." (PMID 22264292, 2012). "Among the involved proteases, MMP-2, MMP-9, u-PA, and cathepsins reportedly play the most important roles in cancer invasion and metastasis." (PMID 22363545, 2012). "The migration and invasion of cancer cells requires breakdown of the extracellular matrix (ECM) and basement membrane by proteases such as MMP-2 and MMP-9." (PMID 22962576, 2012). "Constructive expression of STAT3 can up-regulate the expression of MMP-2 and MMP-9, which are able to efficiently degrade the extracellular matrix and basement membrane, promoting invasion and metastasis of cancer cells." (PMID 22179587, 2012).
cancer (continued). "Several studies confirmed that high preoperative serum or plasma MMP-2, MMP-9 and mainly TIMP-1 antigen levels are strong prognostic factors for patients with CRC and their determination might be useful for identification of patients with higher risk for cancer recurrence." (PMID 23202950, 2012). "Due to the importance of TIMP-1 in cancer cells invasion, and angiogenesis, we have demonstrated that 3-azidoWA treatment augmented the expression of TIMP-1 which is a modulator of MMP-2 expression in both cell lines, in dose dependent manner." (PMID 22962598, 2012). "On the other hand, a strong MMP-2, MMP-9 or MMP-7 signal in cancer cells has been found to predict better survival." (PMID 22200690, 2012). "In our experiment, PE downregulated the expression of MMP-2 and MMP-9, and activated TIMP-2, revealing a double strength anti-cancer effect." (PMID 21799674, 2011). "Because there is high homology in amino acid sequences of MMP-2 among chicken, mice, and humans, a xenogeneic chicken MMP-2 was used as the basis for a vaccine to overcome tolerance in treating cancers in mice and humans." (PMID 21385454, 2011). "It caused significant inhibition in the production and secretion of MMP-2 and MMP-9 by activated monocytes and cancer cells by inhibiting the pro-inflammatory transcription factors NFκB and AP-1." (PMID 21349163, 2011). "MT1-MMP, MMP-2 and MMP-9, which are abundantly expressed in various malignant tumors, contribute to cancer invasion and metastasis." (PMID 21943213, 2011). "Several lines of evidence have indicated that MMP species such as MMP-2, MMP-7, MMP-9 and MMP-14 (MT1-MMP) have key roles in invasion and metastases of cancer cells." (PMID 22015555, 2011). "Among these both, the MMP-2 and MMP-9 contribute much more to the cancer invasiveness and metastasis." (PMID 21799674, 2011). "Snail, an EMT-related protein, mediates the effect of CAGE by inducing matrix metalloproteinase-2 (MMP-2) and cancer cell motility." (PMID 22348197, 2011). "MMP-2 and MMP-9 plasma levels have been reported to be elevated in patients with various types of cancer." (PMID 21726449, 2011). "The present work opens the possibility of developing new therapies and supports the use of the dog as an animal model in this field for studying the role of MMP-2 and MT1-MMP in the mechanism of cancer." (PMID 21726449, 2011). "Among these enzymes, MMP-2, MMP-9 and urokinase plasminogen activator (u-PA) can directly degrade most components of the ECM and are deeply involved in cancer invasion and metastasis." (PMID 19789215, 2011). "Gelatin zymography assays indicated that THL dose-dependently inhibited the secretion of MMP-2 and MMP-9 in MDA-MB-231, H1299, PC-3 and CT-26 cancer cells." (PMID 20429953, 2010). "High level expression of MMP-2 and MMP-9 has been frequently correlated with increased tumor invasion and poor prognosis in various types of human cancer." (PMID 21151448, 2010). "Matrix metalloproteinases (MMPs), including MMP-2, are enzymes involved in the degradation of ECM, which show increased expression during cancer metastasis." (PMID 20701792, 2010). "THL inhibited the migration and invasion ability of various cancer cells in vitro, decreased the secretion of MMP-2, MMP-9, and uPA and the activity of ERK1/2 in cancer cells, and suppressed pulmonary metastasis of CT-26 cancer cells in syngenic mice." (PMID 20429953, 2010). "Previously published work from our lab and others indicate that extracellular hsp90α contributes to the activation of both MMP-2 and HER-2, two proteins involved in cancer metastasis." (PMID 20553606, 2010). "Gelatin zymography showed bands corresponding in size to MMP-2, MMP-3, MMP-9, and MMP-10 enzymes in each of the 24 cancer cases." (PMID 20920372, 2010).
cancer (continued). "Its roles have undergone extensive research in areas of prevention and therapy of cancer; it has been shown that MMP-1 mRNA and MMP-2 and -9 activities are inhibited by glutathione in human fibroblasts and liver allografts, respectively." (PMID 21118526, 2010). "Among them, MMP-2 and MMP-9 are known to be strongly correlated with the metastatic potential of cancer cells and in particular are prognostic factors in many solid tumors." (PMID 20169190, 2010). "Therefore, the suppression of phosphorylation of c-Met and the blockage of PI3K/Akt and NF-κB signaling pathways by the anticancer compounds could possibly inhibit the related downstream targets such as OPN, VEGF, MMP-9 and MMP-2, and thus suppress the cancer progression." (PMID 19796390, 2009). "MMP-2 was reported to play a direct role in OPN-induced cancer cell migration and invasion; OPN-stimulated MMP-2 activation occurred through NF-κB mediation." (PMID 19796390, 2009). "Downstream of the PRL-3-integrin β1-ERK1/2 pathway, we found that MMP2 exerted proteolysis function on ECM, a critical event for cancer metastasis." (PMID 19930715, 2009). "Intriguingly, hypoxia has been shown to upregulate gelatinases (MMP-2 and MMP-9), and to enhance cancer cell invasiveness in vitro." (PMID 19426483, 2009). "In addition, several common cancers have increased levels of MMP-2, which correlates with worse prognosis, suggesting that identifying the Cia5d gene and the pathways controlled by it could potentially generate novel targets relevant to cancer treatment as well." (PMID 18706093, 2008). "Particular MMPs (including MMP-2, MMP-9 and MMP-14) are involved in key events in cancer cells, including proliferation, apoptosis and angiogenesis." (PMID 17894888, 2007). "MMP-2 and MMP-14 mRNA was detected primarily in reactive stromal cells whereas TIMP-2 mRNA was expressed by both stromal and cancer cells." (PMID 16776850, 2006). "In the multivariate analysis, including a broad selection of clinical parameters, the MMP-2 antigen level kept its independent prognostic value, but the significance for the MMP-2 BIA activity level of the carcinomas was lost." (PMID 16538217, 2006). "Gelatinases A (MMP-2) and B (MMP-9) can both degrade type IV collagen of basement membranes, the first barrier for cancer invasion." (PMID 14710236, 2004). "Using the Mann–Whitney U-test the differences in the means between the two groups (normal vs cancer) are highly significant (P-values ⩽0.006), except for the genes b-FGF and MMP-2 (respective P-values: 0.336, 0.584)." (PMID 12189553, 2002). "This is because MMP-2 is recognized as a major MMP whose expression and activity have been closely tied to cell invasion and the metastatic phenotype across a wide range of cancer types, inclusive of PCa." (PMID 41597241, 2026). "Succinylated gelatin enabled the electrostatic conjugation of DOX with gadolinium oxide nanoparticles, and the release of DOX was controlled through the enzymatic degradation of gelatin by matrix metalloproteinases-2 and -9 (MMP-2 and MMP-9), which are highly expressed in cancer cells." (PMID 41893218, 2026). "Elevated levels of MMP‐2 and MMP‐9 are often observed in various cancers." (PMID 41546170, 2026). "Increased MMP-2 and MMP-9 expression has also been reported to correlate with cancer invasion." (PMID 39941886, 2025). "K8/18 depletion leads to hyperactivation of the PI3K/AKT/ nuclear factor kappa B (NF-κB) pathway and increased expression of matrix metalloproteinase 2 (MMP2) and matrix metalloproteinase 9 (MMP9), which prompts the tight junction protein claudin-1 to assume an active role in cancer progression." (PMID 40229242, 2025). "Furthermore, eupatilin markedly decreased both the mRNA expression and enzymatic activities of matrix metalloproteinases (MMP)-2 and MMP-9, indicating its potential to inhibit cancer cell invasion." (PMID 41471692, 2025). "Inhibition of MMP2 and MMP9 has been shown to alleviate cancer progression." (PMID 39895792, 2025).
cancer (continued). "This is because MMP-2 is recognized as a major MMP whose expression and activity has been closely tied to cell invasion and the metastatic phenotype across a wide range of cancer types, inclusive of PCa." (PMID 41509368, 2025). "Additionally, several soluble factors associated with the senescence phenotype were highly expressed in HLA-E positive cancer cells, particularly GDF15, MMP2, and MMP7." (PMID 40959273, 2025). "Modification of cancer biomarkers, such as decreased PCNA and Ki-67, increased Bax/Bcl-2 ratio, increased cleaved caspase-3, decreased VEGF and CD31, and decreased matrix metalloproteinases, especially MMP-2 and MMP-9, were also observed." (PMID 41322296, 2025). "However, the literature confirms that MMP-2 and MMP-9 are often co-released into the extracellular matrix during inflammation, fibrosis, and cancer progression, supporting the need for multiplex biosensing." (PMID 41002342, 2025). "Among the MMP family, MMP-2 and MMP-9 are particularly significant in cancer progression." (PMID 40563423, 2025). "Furthermore, EGCG suppresses the activity of matrix metalloproteinases (MMP-2 or MMP-9), enzymes responsible for extracellular matrix degradation, thereby limiting cancer cell proliferation and invasion." (PMID 40667502, 2025). "In cancer studies, PCB has been reported to inhibit cell proliferation, migration, and promote apoptosis through pathways such as FAK/p38 and PI3K/AKT, with notable effects on MMP2/9 expression." (PMID 41008632, 2025). "Rutin significantly inhibited the migration and invasion of TNBC cells, which may be attributed to its downregulation of matrix metalloproteinases (MMPs) such as MMP-2 and MMP-9, proteins crucial for cancer metastasis." (PMID 39802656, 2025). "Specifically, MMP2 and MMP9 are frequently overexpressed in aggressive tumors and play a key role in degrading the ECM, particularly the basal membrane, thus contributing to cancer metastasis." (PMID 41226554, 2025). "Moreover, it was observed that CARHSP1 increased the expression of MMP2 and MMP9 at the mRNA level and the protein level, which play vital roles in tissue remodeling, cancer progression, and metastasis." (PMID 40055805, 2025). "Elevated levels of MMPs, particularly MMP-2 and MMP-9, often correlate with increased chemokine levels, reflecting a complex interplay between these proteases and chemokine signaling in cancer." (PMID 39409924, 2024). "Given the reported predictive role of MMP-2 and/or MMP-9 overexpression in metastatic progression in various cancers, we sought to investigate whether MMP-2 and/or MMP-9 genotypes were linked to metastatic risk in UTUC." (PMID 39063556, 2024). "In fact, it has been reported that in cancer cells, the GCX functions as a mechanosensory organ that senses interstitial flow, and affects the expression of matrix metalloproteinase‐1 (MMP‐1), MMP‐2, CD44, and α3 integrin which regulate cell motility and metastasis induced by interstitial flow." (PMID 39300946, 2024). "Therefore, targeting MMPs, specifically MMP-2 and MMP-9, represents a promising new therapeutics avenue for inhibiting cancer metastasis." (PMID 39431222, 2024). "MMP2 and PDPN were highly expressed in less than half of cancers." (PMID 39335130, 2024). "Additionally, the interaction of Ox-LDL with LOX-1 activates NF-κB target genes like VEGF, MMP-2, and MMP-9 to encourage the growth, invasion, and angiogenesis of cancer cells." (PMID 39290325, 2024). "Furthermore, the promise of suppressing cancer metastasis is further supported by the antimetastatic effect of reducing ICAM and VCAM activities; furthermore, it downregulates MMP2-9 gene expression." (PMID 38773159, 2024). "MMP-2 and MMP-9 are highly expressed in various cancer cells and targeting MMPs with their inhibitors may act as an important therapeutics in cancers." (PMID 39062100, 2024).
cancer (continued). "Similar to MMP-2, MMP-9 (also known as gelatinase B) degrades gelatin and type IV collagen, and exosomal thrombospondin-1 (THBS1) binds to FAK and MMP-9 to prevent ECM stiffness-dependent cancer invasion." (PMID 38544822, 2024). "In addition, both compounds decrease the MMP-2 and MMP-9 expression, which are important biomarkers of cancer progression and MAPK signaling." (PMID 39272835, 2024). "Therefore, a metal matrix protease-2 (MMP-2) and endogenous GSH dual-responsive liposomal-based nanovesicle, co-loading with 5-FU (anti-cancer drug) and NLG919 (IDO1 inhibitor), was constructed (named as ENP919@5-FU)." (PMID 38755645, 2024). "Taken together, these results highlight the spatial specificity with which cell-penetrating peptides cloaked in an MMP-2/9-sensitive scaffold as an ACPP can target conjugated drug payloads to tumors in commonly used pre-clinical xenograft and syngeneic murine cancer models." (PMID 39683778, 2024). "Although we have shown that SNPs in MMP2 and MMP9 are associated with increased risks of UTUC and metastasis, the effect of individual SNPs on cancer risks and outcomes is modest and not clinically applicable." (PMID 39063556, 2024). "Cancer stem cells from different tumors show IL-1- and TNF receptor superfamily (TNFSF)-dependent NF-κB activation that determines the transcription of EMT genes, such as NANOG, SNAIL, SLUG, ZEB1, ZEB2, and TWIST, as well MMP-2 and MMP-9." (PMID 39519020, 2024). "ATRA is the major biologically active form of vitamin A and may selectively regulate the expression and activity of matrix metalloproteinases (MMPs), such as MMP-2 and MMP-9, in cancer progression and metastasis." (PMID 38732186, 2024). "Pre-clinical studies employing both in vitro and animal models suggest that they mostly act by inhibiting MMP-2 and MMP-9 or their related pathways, indicating that polyphenolic compounds have considerable potential against the development and progression of cancers." (PMID 39335164, 2024). "Although the expression of the MMP-9 and MMP-2 protein was elevated, it is likely that most cancer cells have not evolved to metastasis." (PMID 38955827, 2024). "Therefore, the interplay between the RAS/ERK pathway and N-cadherin, vimentin, and E-cadherin, as well as MMP-2 and MMP-9, is crucial for cancer cell proliferation and migration." (PMID 39769029, 2024). "Several studies have demonstrated that MMP1, MMP2, MMP9, MMP13 and MMP19 in some cancer tissues such as NSCLC or gastric cancer are all raised, and these MMP members can degrade basement membrane and open the channel for cancer’s invasion and metastasis." (PMID 38560562, 2024). "High specificity for MMP-2 and MMP-9 reduces off-target effects and toxicity, providing a more targeted approach to cancer treatment, and these inhibitors also can be used in combination with other therapies, such as chemotherapy, radiation, and immunotherapy, to enhance treatment efficacy." (PMID 39858430, 2024). "The findings suggest that MMP-2 and MMP-9 may play crucial roles in the development of cancer, with MMP-2 serving as a potential biological marker for invasion and lymph node metastasis in OSCC." (PMID 38673838, 2024). "A reduction in MMP-2 or TNC may result in inhibition of the proliferation, migration, and invasion of cancer cells as well as decreased angiogenesis and premetastatic niche formation." (PMID 38360633, 2024). "In fact, in other contexts, overexpression of Rab11a has been shown to contribute to the proliferation and invasion of cancer cells via increased signaling of ERK, PI3K/AKT, EGFR, WNT, and MMP2, consistent with our findings that increased Rab11 activity can drive angiogenesis." (PMID 38903077, 2024). "Moreover, p38/NF-kB-mediated transcription products such as TNF-α, MMPs (MMP-2 and MMP-9), VEGF (also called VEGF-A and located at chromosome 6p12), VEGF-C, and PGE1/2 facilitate the invasion and metastasis of cancer (34, 41,)." (PMID 36993955, 2023).